SYT11 (synaptotagmin 11)
Diseases named in the same sentence as SYT11 in open-access papers (continued):
Sharing a sentence is not in itself a finding about the gene and the disease.
tumor (7 papers, 2015 to 2025). "Genetic alteration profiling of SYT11 revealed that amplification is the most common type of tumor, including UCS and missense mutations." (PMID 38890718, 2024). "This study comprehensively explored the underlying molecular role of SYT11 in different tumor types and clinical prognoses using bioinformatics." (PMID 38890718, 2024). "Furthermore, the elevated expression of the SYT11 gene has been associated with a poorer prognosis in various tumor types, providing additional evidence to support its potential as a diagnostic marker for PCPG." (PMID 38526709, 2025). "Since promoter methylation alters gene expression, we explored the promoter methylation level of SYT11 in tumor and normal tissues using the ULCAN database." (PMID 38890718, 2024). "In this study, we aimed to summarize the clinical significance and molecular landscape of SYT11 in various tumor types." (PMID 38890718, 2024). "TCGA and Genotype-Tissue Expression (GTEx) showed that SYT11 was widely expressed across tumor and corresponding normal tissues." (PMID 38890718, 2024). "The Shiny Methylation Analysis Resource Tool (SMART) database was used to analyze the difference in SYT11 methylation levels between normal and primary tumor tissues." (PMID 38890718, 2024). "Since immune cell infiltration plays a crucial role in tumor progression, we investigated the relationship between SYT11 expression and immune cell infiltration in various tumors." (PMID 38890718, 2024). "Collectively, these findings suggest that abnormal SYT11 expression plays a role in the relationship between immune subsets and anti-tumor immunity." (PMID 38890718, 2024). "SNU484 cells infected with SYT11 shRNA (shSYT11) exhibited reduced spheroid formation, mouse tumor formation, and liver metastasis, suggesting a pro-oncogenic role of SYT11." (PMID 35768842, 2022). "The expression of Synaptotagmin (SYT11) in the tumor tissues of patients with GC was confirmed by performing Immunohistochemistry, and the correlation between the expression level and the patient’s survival rate was analyzed." (PMID 35768842, 2022). "SYT11 affected similarly tumor formation in in vivo xenografts using shSYT11-expressing lentivirus-infected SNU484 cells." (PMID 35768842, 2022). "Four genes, CAMK2N1, CGNL1, DLC1 and SYT11, the expression of which was lower in the tumor tissues than in the normal tissues, were enriched in the cell junction." (PMID 25789025, 2015). "To test whether these genes regulate tumor cell growth we knocked down each of these genes (Ptgds, Arl2bp, Rnf157, and Syt11) in the KP cell line." (PMID 40047406, 2025). "Furthermore, we produced SYT11 transgenic (SYT11-Tg) mice to confirm the effect of SYT11 overexpression on tumor metastasis." (PMID 35768842, 2022). "We then observed that SYT11-ASO reduced tumor formation in a xenograft model." (PMID 35768842, 2022). "In addition, three genes, MAP1LC3A, PRRX1 and SYT11, were moderately downregulated in the tumor tissues." (PMID 25789025, 2015). "Compared with the normal group, the expression of DDC and SYT11 were remarkably up-regulated in the tumor group, while the expression of GCLM, PSMB7, TYRO3, and AGMAT were remarkably down-regulated in the tumor group." (PMID 38526709, 2025). "Interestingly, these SYT11 co-occurring genes were enriched in pathways fundamental to cell function and metabolism, such as transcriptional regulation, cell survival, G protein-coupled signaling pathway, and ER function, which play an important role in tumor progression." (PMID 38890718, 2024). "In epigenetic analyses, such as promoter methylation profiling, SYT11 was hypomethylated in most tumor types than that in normal tissues, while the SYT11 expression was not consistent." (PMID 38890718, 2024).
cancer (4 papers, 2022 to 2025). A tumor composed of atypical neoplastic, often pleomorphic cells that invade other tissues. "Herein, we found that SYT11 expression is closely associated with immune components in various cancers and that SYT11 expression was weakly correlated with B-cell and NK cell immunity, but highly correlated with CAFs." (PMID 38890718, 2024). "Since genetic alterations are closely associated with tumorigenesis, the genetic variation of SYT11 in various cancers were determined using the cBioPortal TCGA cohort." (PMID 38890718, 2024). "In addition, SYT11 expression positively correlated with cancer-associated fibroblasts (CAFs) in most cancer types, except for DLBC, GBM, SARC, and UCS." (PMID 38890718, 2024). "Conversely, the hsa-let-7i-5p/SYT11 pair was positively associated with most cancers." (PMID 38890718, 2024). "Importantly, to the best of our knowledge, we are the first to report the association of SYT11 expression with various components of the TME in multiple cancer types." (PMID 38890718, 2024). "Our findings provide new insights into the potential use of SYT11 as a prognostic biomarker and therapeutic target for cancer." (PMID 38890718, 2024). "The critical role of SYT11 in cancer highlights its clinical value as a prognostic biomarker for various types of cancer." (PMID 38890718, 2024). "Meanwhile, SYT11 expression was linked to diverse OS and DFS outcomes and poor prognosis in most highly expressed cancers." (PMID 38890718, 2024). "In this study, we examined the expression profile and prognostic value of SYT11 in various cancer types." (PMID 38890718, 2024). "Based on meta-profile heatmap, hsa-miR-19a-3p, hsa-let-7g-5p, hsa-let-7i-5p, and hsa-miR-98-5p showed significant differential expression in tissue samples of cancer patients and healthy participants, and presented binding sites with SYT11 3′-UTR." (PMID 38890718, 2024). "Since SYT11 expression is downregulated in various cancers, regulatory miRNAs are possibly highly expressed in cancer." (PMID 38890718, 2024). "SYT11 expression was significantly positively associated with CD8 + T cell (in 14 types of cancer) and macrophage (in 13 types of cancer) infiltration." (PMID 38890718, 2024). "As combination therapy is preferred against most cancers, finding a combination therapy drug with SYT11 is essential for increasing treatment efficacy." (PMID 35768842, 2022). "However, owing to the importance of SYT11 in several cancers, new role of SYT11 in various cancers should be investigated." (PMID 38890718, 2024). "Our results provide a clear understanding of the role of SYT11 in various cancer types and suggest that SYT11 may be of prognostic and clinical significance." (PMID 38890718, 2024). "Survival analysis showed that SYT11 expression correlated with the prognosis of seven cancer types." (PMID 38890718, 2024). "Additionally, SYT11 mRNA expression was not affected by promoter methylation, but regulated by certain miRNAs and associated with cancer patient prognosis." (PMID 38890718, 2024). "Interestingly, SYT11 expression in myeloid-derived suppressor cells (MDSCs) showed a significant negative association with almost all cancer types, excluding ACC, MESO, OV, SKCM, and UCEC, while these negative correlations were associated with few CD8 + T cells and macrophages." (PMID 38890718, 2024). "In this context, given the lack of an in-depth understanding of the role of SYT11, using pan-cancer analysis to investigate its roles in biological and pathological processes is an attractive approach, specifically to assess its value for cancer treatment." (PMID 38890718, 2024). "However, no study describes the cancer-related SYT11 functions and mechanisms." (PMID 35768842, 2022).
adenocarcinoma (1 paper, 2022). A common cancer characterized by the presence of malignant glandular cells. "We observed that 77.5 and 46.7% of the diffuse-type GC tissue and adenocarcinoma samples exhibited a high-level SYT11 protein expression, respectively." (PMID 35768842, 2022).
SYT11 also shares sentences with these, for which no sentence is quoted: dementia (2 papers); epilepsy (2); neurological diseases (2); Adrenocortical Cancer (1); autism (1); Bladder Cancer (1); clear cell renal cell carcinoma (1); colorectal cancer (1); diffuse large B-cell lymphoma (1); esophageal carcinoma (1); Graves disease (1); Huntington disease (1); infection (1); lupus (1); lymphoid neoplasm (1); mesothelioma (1); multiple sclerosis (1); neuroblastoma (1); neurodegenerative disease (1); ocular melanoma (1); ovarian serous cystadenocarcinoma (1); pancreatic ductal adenocarcinoma (1); Rett syndrome (1); sarcoma (1); skin cutaneous melanoma (1); Stroke (1); testicular germ cell tumor (1); thyroid carcinoma (1); uterine carcinosarcoma (1).